OR1D2 (olfactory receptor family 1 subfamily D member 2)
Description:
Odorant receptor which may be involved in sperm chemotaxis. Bourgeonal is a strong chemoattractant for sperm in vitro and is shown to be a strong agonist for OR1D2 in vitro. May also function in olfactory reception.
Synonyms: OR17-4; OLFR1
Tractability: Small molecule: it belongs to a druggable protein family. Antibody: UniProt places it where antibodies can reach, with high confidence; its Gene Ontology location is reachable by antibodies, with high confidence; UniProt predicts a signal peptide or a membrane-spanning region.
Gene: Protein-coding gene on chromosome 17 (3,088,484 to 3,104,422, reverse strand). Ensembl gene ENSG00000184166.
Subcellular location: Cell membrane
Pathways (Reactome):
Sensory Perception: Expression and translocation of olfactory receptors; Olfactory Signaling Pathway
Gene Ontology:
Molecular function: identical protein binding; olfactory receptor activity; G protein-coupled receptor activity
Biological process: G protein-coupled receptor signaling pathway; sensory perception of smell; signal transduction; detection of chemical stimulus involved in sensory perception of smell
Cellular component: plasma membrane; membrane
Genetic constraint (gnomAD): Loss-of-function variants: 0 observed, 3 expected, observed/expected ratio (o/e) 0, 90% interval 0 to 0.98. That is too few expected variants to judge how well the gene tolerates losing a copy. Missense variants: 357 observed, 393.93 expected, observed/expected ratio (o/e) 0.91, 90% interval 0.83 to 0.99. Synonymous variants: 157 observed, 160.56 expected, observed/expected ratio (o/e) 0.98, 90% interval 0.86 to 1.12.
Homologues: Orthologues: chimpanzee OR1D2 (98% identical), mouse Or1d2 (87% identical), rat Or1d2 (86% identical), rat Olr1520 (85% identical). Paralogues in human: OR1D5 (82% identical), OR7D4 (54% identical), OR7C1 (53% identical), OR1N2 (53% identical), OR7A10 (52% identical), OR7D2 (51% identical), OR1G1 (51% identical), OR1N1 (51% identical), OR7A5 (51% identical), OR7C2 (51% identical), OR7G3 (51% identical), OR1E1 (50% identical), and 116 more.
Diseases named in the same sentence as OR1D2 in open-access papers:
OR1D2 is named in the same sentence as 3 diseases in open-access papers, as found by Europe PMC text mining. Sharing a sentence is not in itself a finding about the gene and the disease. The quoted sentences say what the papers report.
Infertility (1 paper, 2021). "Thirteen single nucleotide polymorphisms of the OR1D2 gene in the men suffering unexplained infertility were documented." (PMID 34449557, 2021).
OR1D2 also shares sentences with these, for which no sentence is quoted: colorectal cancer (1 paper); prostate carcinoma (1).